RBM15 (RNA binding motif protein 15)
Description:
RNA-binding protein that acts as a key regulator of N6-methyladenosine (m6A) methylation of RNAs, thereby regulating different processes, such as hematopoietic cell homeostasis, alternative splicing of mRNAs and X chromosome inactivation mediated by Xist RNA. Associated component of the WMM complex, a complex that mediates N6-methyladenosine (m6A) methylation of RNAs, a modification that plays a role in the efficiency of mRNA splicing and RNA processing (By similarity). Plays a key role in m6A methylation, possibly by binding target RNAs and recruiting the WMM complex. Involved in random X inactivation mediated by Xist RNA: acts by binding Xist RNA and recruiting the WMM complex, which mediates m6A methylation, leading to target YTHDC1 reader on Xist RNA and promoting transcription repression activity of Xist. Required for the development of multiple tissues, such as the maintenance of the homeostasis of long-term hematopoietic stem cells and for megakaryocyte (MK) and B-cell differentiation (By similarity). Regulates megakaryocyte differentiation by regulating alternative splicing of genes important for megakaryocyte differentiation; probably regulates alternative splicing via m6A regulation. Required for placental vascular branching morphogenesis and embryonic development of the heart and spleen (By similarity). Acts as a regulator of thrombopoietin response in hematopoietic stem cells by regulating alternative splicing of MPL (By similarity). May also function as an mRNA export factor, stimulating export and expression of RTE-containing mRNAs which are present in many retrotransposons that require to be exported prior to splicing. High affinity binding of pre-mRNA to RBM15 may allow targeting of the mRNP to the export helicase DBP5 in a manner that is independent of splicing-mediated NXF1 deposition, resulting in export prior to splicing. May be implicated in HOX gene regulation.
Synonyms: OTT; OTT1
Tractability: Antibody: UniProt places it where antibodies can reach, with high confidence. PROTAC: UniProt records ubiquitination sites on it; ubiquitination databases record sites on it; its protein half-life has been measured.
Gene: Protein-coding gene on chromosome 1 (110,338,506 to 110,346,681, forward strand). Ensembl gene ENSG00000162775.
Subcellular location: Nucleus speckle; Nucleus, nucleoplasm; Nucleus envelope; Nucleus membrane
Subcellular location (Human Protein Atlas): Nucleoplasm
Gene Ontology:
Molecular function: mRNA binding; protein binding; RNA binding; nucleic acid binding
Biological process: dosage compensation by inactivation of X chromosome; negative regulation of DNA-templated transcription; regulation of alternative mRNA splicing, via spliceosome; regulation of megakaryocyte differentiation; RNA methylation; thrombopoietin-mediated signaling pathway; regulation of myeloid cell differentiation
Cellular component: nuclear envelope; nuclear membrane; nuclear speck; nucleoplasm; RNA N6-methyladenosine methyltransferase complex; nucleus
Genetic constraint (gnomAD): Loss-of-function variants: 7 observed, 63.21 expected, observed/expected ratio (o/e) 0.11, 90% interval 0.062 to 0.21. The upper end of that interval is the gene's LOEUF score, 0.21, which puts it in group 1 of 6, group 1 being the genes least tolerant of losing a copy. Missense variants: 1,133 observed, 1,344.5 expected, observed/expected ratio (o/e) 0.84, 90% interval 0.8 to 0.88. Synonymous variants: 598 observed, 525.97 expected, observed/expected ratio (o/e) 1.14, 90% interval 1.06 to 1.22.
Homologues: Orthologues: chimpanzee RBM15 (100% identical), pig RBM15 (97% identical), rabbit RBM15 (96% identical), dog RBM15 (96% identical), guinea pig RBM15 (95% identical), rat Rbm15 (93% identical), macaque RBM15 (93% identical), mouse Rbm15 (93% identical), zebrafish rbm15 (59% identical), tropical clawed frog rbm15 (57% identical), Drosophila melanogaster nito (31% identical), Drosophila melanogaster nonA (8% identical), and 1 more. Paralogues in human: RBM15B (39% identical), SPEN (25% identical), RAVER1 (10% identical), SFPQ (9% identical), PSPC1 (8% identical), NONO (8% identical), RAVER2 (7% identical).
Diseases named in the same sentence as RBM15 in open-access papers:
RBM15 is named in the same sentence as 103 diseases in open-access papers, as found by Europe PMC text mining. Sharing a sentence is not in itself a finding about the gene and the disease. The quoted sentences say what the papers report.
acute megakaryoblastic leukemia (19 papers, 2012 to 2025). Acute megakaryoblastic leukemia (AMKL) is a form of acute myeloid leukemia (AML) that occurs predominantly in childhood and particularly in children with Down syndrome (DS-AMKL). "In conclusion, we describe a case of acute megakaryoblastic leukemia (AMKL) with RBM15::MRTFA fusion associated with severe hepatic fibrosis and portal hypertension that resolved with chemotherapy." (PMID 39281382, 2024). "The fusion of MKL1 and the RNA-binding motif protein-15 gene is associated with a specific translocation event in acute megakaryocytic leukemia." (PMID 34761735, 2022). "Previous research has linked the incorrect control of RBM15 with an increased risk of certain cancers, including megakaryocytic leukemia." (PMID 26575292, 2015). "The Rbm15-Mkl1 fusion protein is associated with acute megakaryoblastic leukemia (AMKL), although little is known regarding the molecular mechanism(s) whereby this fusion protein contributes to leukemogenesis." (PMID 22927943, 2012). "RBM15 was initially identified as a leukemic ectopic which participates in pediatric acute megakaryocytic leukemia." (PMID 36803098, 2023). "It is indispensable for megakaryocyte differentiation, and rbm15 defect can induce acute megakaryoblast leukemia." (PMID 32518161, 2020). "The overlapping region between AS-RBM15 RNA and 5′ UTR of RBM15 mRNA functions as an enhancer of RBM15 protein synthesis in megakaryocytic leukemia." (PMID 33419342, 2020). "Different from IGF2BP2 and IGF2BP3, although the oncogenic roles of YTHDC2 and RBM15 have been identified in colon cancer and acute megakaryoblastic leukemia, their functions in breast cancer await to be identified." (PMID 33585234, 2020). "Overexpression of PRMT1 in acute megakaryocytic leukemia cell lines blocks megakaryocyte terminal differentiation by downregulation of RBM15 protein level." (PMID 26575292, 2015). "Recent studies have revealed the involvement of RBM15 in cellular biological behaviors such as proliferation, invasion, migration, and apoptosis in various cancers, like acute megakaryocytic leukemia, colorectal cancer, ovarian cancer, laryngeal squamous cell carcinoma and osteosarcoma." (PMID 38915367, 2024). "RBM15 also contributed to chromosomal translocation in acute megakaryocytic leukemia." (PMID 35433701, 2022). "Initially identified as an ectopic gene in pediatric acute megakaryocytic leukemia, RBM15, despite lacking methylation activity, plays a critical role in recruiting MTCs and facilitating their binding to target mRNAs as a member of the m6A writers." (PMID 38915367, 2024). "Recent studies have shown that RNA binding protein RBM15 could be methylated by PRMT1, which resulted in RBM15 degradation via ubiquitylation and retardation of megakaryocyte differentiation in acute megakaryocytic leukemia (AMKL)." (PMID 37558663, 2023). "Extramedullary involvement of acute myeloid leukemia (AML), aka myeloid sarcoma, is a rare phenomenon in acute megakaryoblastic leukemia with RBM15:: MRTFA(MKL1) fusion, which might mimic non-hematologic malignancies." (PMID 38374236, 2025).
breast carcinoma (18 papers, 2016 to 2025). "In basal-like breast cancer, RBM15 is markedly upregulated and associated with poor clinical prognosis." (PMID 41403702, 2025). "Studies show RBM15 is highly active in a type of breast cancer called triple-negative and is linked to patient outcomes." (PMID 38825643, 2024). "Activation of the core reactive pathway, comprised of stromal proteins, Claudin7, E-cadherin, Beta-catenin, RBM15 and Caveolin1, was first discovered as associated with poor survival in breast cancers {Ha, 2018 #345}." (PMID 37790408, 2023). "For instance, RBM15 upregulation in acute myeloid leukemia, hepatocellular carcinoma, and breast cancer is associated with accelerated tumor progression and unfavorable outcomes, whereas its downregulation in certain solid tumors may reflect impaired tumor-suppressive pathways." (PMID 41403702, 2025). "In breast cancer, both RBM15 and karyopherin subunit alpha 2 (KPNA2) are significantly overexpressed in tissues and cell lines." (PMID 41403702, 2025). "In summary, RBM15 drives breast cancer progression by promoting metabolic reprogramming, stabilizing oncogenic transcripts, and conferring chemotherapy resistance, thereby representing a crucial therapeutic target in aggressive breast cancer subtypes." (PMID 41403702, 2025). "In recent years, the role of RBM15 in a variety of cancers has gradually attracted attention, especially in breast cancer." (PMID 40830812, 2025). "Knockdown of RBM15 suppresses proliferation, migration, and invasion of breast cancer cells in vitro, while enhancing lymphocyte immune activity." (PMID 41403702, 2025). "In breast cancer, RBM15 exerts profound oncogenic functions, particularly in basal-like and triple-negative subtypes." (PMID 41403702, 2025). "In various solid tumors, including hepatocellular carcinoma, breast cancer, gastric cancer, and lung cancer, aberrant RBM15 expression has been correlated with enhanced proliferation, resistance to apoptosis, increased metastatic potential, and poor patient prognosis." (PMID 41403702, 2025). "Notably, the tumor-promoting effects of RBM15 largely depend on enhanced serine–glycine metabolism, underscoring its role as a metabolic regulator and therapeutic target in breast cancer." (PMID 41403702, 2025). "In breast cancer tissues and cells, both RBM15 and KPNA2 are highly expressed." (PMID 41403702, 2025). "Our study revealed that RBM15 could unexpectedly regulate serine and glycine metabolism in breast cancer (BC) cells." (PMID 38825643, 2024). "Apart from RBM15, which has been reported to recruit the core m6A methyltransferase to specific sites via recognition of U-rich sequences, none of the other components of the m6A methyltransferase complex show increased expression in breast cancers." (PMID 37208522, 2023). "Mechanistic studies demonstrated that RBM15 stabilizes KPNA2 mRNA via m6A modification, thereby promoting breast cancer progression." (PMID 41403702, 2025). "In the current study, we identified significantly elevated levels of RBM15, an m6A writer, in basal-like breast cancer (BC) patients compared to nonbasal-like BC patients and linked this increase to worse clinical outcomes." (PMID 38825643, 2024). "RBM15, regulated by BARX2 and ER, has been reported to affect cell growth and invasion in breast cancer samples." (PMID 37686507, 2023). "Other subunits of METTL3 complex, namely WTAP, RBM15, KIAA1429 (also known as Virilizer homolog or VIRMA), and METTL14, displayed moderate-to-strong staining intensities in both normal and breast cancer tissues." (PMID 36289222, 2022). "Among them, the expression of RBM15, VIRMA, HNRNPA2B1, and YTHDF1/2/3 were significantly upregulated, but METTL3, METTL14, METTL16, WTAP, FTO, YTHDC1, and EIF3A had lower expression in breast cancer compared to normal samples." (PMID 34804948, 2021). "METTL3, METTL16, ZC3H13, YTHDC1 and FTO were expressed at a low level in breast cancer, while KIAA1429, RBM15, and YTHDF1 were expressed at a high level." (PMID 33362863, 2020).
breast carcinoma (continued). "Studies have shown that the expression level of RBM15 in breast cancer tissues is usually higher than that in normal breast tissues." (PMID 40830812, 2025). "In this study, we used a series of bioinformatic databases and tools to jointly analyze the expression of m6A methylation transferases (METTL3, METTL14, WTAP, RBM15, RBM15B and ZC3H13) and investigate the prognostic value of METTL14 and ZC3H13 in breast cancer." (PMID 33363011, 2020). "The expression of METTL3, METTL14, RBM15B, and ZC3H13, but not of WTAP and RBM15, was significantly decreased in breast cancer." (PMID 33363011, 2020). "In this study, we used Oncomine and The Cancer Genome Atlas (TCGA) databases to jointly analyze the expression of m6A “writer” in breast cancer including METTL3, METTL14, WTAP, RBM15, RBM15B, and ZC3H13, indicating that the mRNA expression levels of METTL14 and ZC3H13 were lower in tumor samples." (PMID 33363011, 2020). "Barx2 increased expression of both ESR1 isoforms, the estrogen-responsive genes (SOX5, RBM15 and Dynein), the tissue inhibitor of metalloproteinase (TIMP) genes (TIMP1 and TIMP3), and MMP-9, all of which promote breast cancer cell growth, survival, and invasion." (PMID 27533254, 2016). "The abundance of RBM15 and ALKBH5 in lung cancer cell lines exhibited a negative correlation with those in breast cancer cell lines." (PMID 38665783, 2024).
hepatocellular carcinoma (18 papers, 2020 to 2026). A malignant tumor that arises from hepatocytes. "In addition, high expression of RBM15 affects the prognosis of HBV-associated hepatocellular carcinoma patients." (PMID 35223996, 2022). "RBM15 modulates m6A modification of YES proto-oncogene 1 (YES1) mRNA in an IGF2BP1-dependent manner, promoting hepatocellular carcinoma progression, indicating RBM15/IGF2BP1 regulates the m6A modification of other genes in other diseases." (PMID 40592832, 2025). "Hepatitis B virus (HBV) infection upregulates RBM15 expression through its X protein (HBx), thereby contributing to the pathogenesis of hepatocellular carcinoma." (PMID 41403702, 2025). "RBM34 and RBM15 played an oncogenic function in hepatocellular carcinoma and PC progression, respectively." (PMID 39741300, 2024). "RBM15, which is a member of the split ends family of proteins, determines cell-fate in many tissues including blood and is overexpressed in hepatocellular carcinoma." (PMID 35288483, 2022). "Here, 13 differentially expressed m6A methylation regulators were confirmed in 374 hepatocellular carcinoma (HCC) patients, among which RBM15, YTHDC1, YTHDF1, and YTHDF2 were significantly variant in different stages and grades." (PMID 32974160, 2020). "RBM15B, the paralog of RBM15, was found involved in prognostic models of several types of tumors, such as alcohol-related hepatocellular carcinoma (A-HCC), small cell lung cancer (SCLC), and melanoma." (PMID 37818090, 2023). "RBM15 also regulated the IGF2BP1-YES1-MAPK signaling axis through the m6A modification mechanism and accelerated the progression of hepatocellular carcinoma." (PMID 40830812, 2025). "In hepatocellular carcinoma (HCC), RBM15 plays a vital role in tumor progression, particularly in regulating angiogenesis." (PMID 41403702, 2025). "In hepatocellular carcinoma, m6A methylation of vascular endothelial growth factor A (VEGFA) mRNA was modified by methyltransferase RBM15 and two readers, YTHDF2 and IGF2BP3." (PMID 41272900, 2025). "RBM15 can also regulate YES1 m6A modification in an IGF2BP1-dependent manner, promoting the development of hepatocellular carcinoma." (PMID 40435202, 2025). "For instance, RBM15 can interact with IGF2BP1 to facilitate the post-transcriptional activation of YES proto-oncogene 1 (YES1), thus contributing to the regulation of hepatocellular carcinoma progression." (PMID 38915367, 2024). "RBM15 and RBMX facilitate the proliferation and invasiveness of tumors, such as hepatocellular carcinoma." (PMID 36171892, 2022). "Furthermore, m6A regulators, such as RBM15, METTL14 were also demonstrated to act as prognosis markers in multiple cancers, such as pancreatic cancer and hepatocellular carcinoma." (PMID 35847857, 2022). "The function of the N6-methyladenosine (m6A) methyltransferase RNA-binding motif protein 15 (RBM15) in hepatocellular carcinoma (HCC) has not been thoroughly investigated." (PMID 34707107, 2021).
laryngeal squamous cell carcinoma (15 papers, 2021 to 2026). A squamous cell carcinoma that arises from the larynx. "Among the m6A methyltransferases, RBM15 has been implicated in promoting cancer progression through m6A modification in various cancers, including laryngeal squamous cell carcinoma, pancreatic cancer, and colorectal cancer." (PMID 39716068, 2024). "RBM15‐mediated m6A modification of BAX inhibitor motif containing 6 (TMBIM6) by recruiting IGF2BP3 to promote the progression of laryngeal squamous cell carcinoma." (PMID 40923717, 2026). "For example, Overexpression of RBM15 increased laryngeal squamous cell carcinoma cell proliferation, migration, invasion, and apoptosis by regulating TMBIM6 stability in an IGF2BP3-dependent manner." (PMID 38765115, 2024). "For instance, in laryngeal squamous cell carcinoma, RBM15 enhances the malignant progression by promoting m6A modification of TMBIM6, thereby increasing TMBIM6 mRNA levels." (PMID 39716068, 2024). "It has been reported that RBM15 plays an important role in the progress of laryngeal squamous cell carcinoma (LSCC), promoting LSCC migration and invasion." (PMID 35223996, 2022). "Study has shown that RBM15 promoted the progression of laryngeal squamous cell carcinoma (LSCC) by mediating the m6A modification of TMBIM6 mRNA." (PMID 35223996, 2022). "RNA binding motif protein 15 (RBM15) contributes to the progression of laryngeal squamous cell carcinoma." (PMID 36536402, 2022). "RBM15 was markedly upregulated in laryngeal squamous cell carcinoma and correlated with a worse prognosis." (PMID 35655464, 2022). "Third, TMBIM6, as a mediating gene discovered for HNSC, played an important role in the progression of laryngeal squamous cell carcinoma as a downstream target of RBM15-mediated N6-methyladenosine modification." (PMID 34464378, 2021). "RBM15 has been manifested to mediate m6A modification of transmembrane BAX inhibitor motif containing 6 (TMBIM6) mRNA via depending on the reader protein IGF2BP3 in laryngeal squamous cell carcinoma." (PMID 41272900, 2025). "Moreover, RBM15 has been reported to promote the occurrence and development of laryngeal squamous cell carcinoma by maintaining the stability of TMBIM6." (PMID 36803098, 2023). "The m6A modification of TMBIM6 mediated by RBM15 increases its stability in an IGF2BP3-dependent manner, promoting the development and progression of laryngeal squamous cell carcinoma." (PMID 40435202, 2025). "RBM15 regulates the stability of TMBIM6 in an IGF2BP3-dependent manner, promoting the progression of laryngeal squamous cell carcinoma." (PMID 39039611, 2024). "In laryngeal carcinoma, RBM15 and IGF2BP3 are involved in m6A methylation modification of TMBIM6, thereby regulating the expression of TMBIM6 in laryngeal squamous cell carcinoma (LSCC)." (PMID 36793593, 2023). "Additionally, RBM15 may interact with Insulin-like growth factor 2 mRNA-binding protein 3 (IGF2BP3) and collaborate in the m6A modification of TMBIM6, consequently promoting the malignant progression of laryngeal squamous cell carcinoma." (PMID 38915367, 2024).